RPL35A (ribosomal protein L35a)
Description:
Component of the large ribosomal subunit. The ribosome is a large ribonucleoprotein complex responsible for the synthesis of proteins in the cell. Required for the proliferation and viability of hematopoietic cells.
Synonyms: GIG33; L35A; eL33; DBA5
Tractability: Small molecule: an approved drug acts on it; a structure with a bound ligand is known; a high-quality ligand is known. PROTAC: ubiquitination databases record sites on it; its protein half-life has been measured; a small molecule that binds it is known. Other modalities: a drug acting on it is in phase 2 or 3 trials.
Target class: Other cytosolic protein
Gene: Protein-coding gene on chromosome 3 (197,950,000 to 197,956,610, forward strand). Ensembl gene ENSG00000182899.
Subcellular location: Cytoplasm
Pathways (Reactome):
Metabolism of proteins: Eukaryotic Translation Termination; Formation of a pool of free 40S subunits; GTP hydrolysis and joining of the 60S ribosomal subunit; L13a-mediated translational silencing of Ceruloplasmin expression; PELO:HBS1L and ABCE1 dissociate a ribosome on a non-stop mRNA; Peptide chain elongation; Ribosome Quality Control (RQC) complex extracts and degrades nascent peptide; SRP-dependent cotranslational protein targeting to membrane; ZNF598 and the Ribosome-associated Quality Trigger (RQT) complex dissociate a ribosome stalled on a no-go mRNA
Metabolism of RNA: Major pathway of rRNA processing in the nucleolus and cytosol; Nonsense Mediated Decay (NMD) enhanced by the Exon Junction Complex (EJC); Nonsense Mediated Decay (NMD) independent of the Exon Junction Complex (EJC)
Cellular responses to stimuli: Response of EIF2AK4 (GCN2) to amino acid deficiency
Developmental Biology: Regulation of expression of SLITs and ROBOs
Disease: Viral mRNA Translation
Metabolism: Selenocysteine synthesis
Gene Ontology:
Molecular function: protein binding; RNA binding; structural constituent of ribosome
Biological process: ribosomal large subunit biogenesis; rRNA processing; cytoplasmic translation; negative regulation of myoblast fusion; spermatogenesis; striated muscle contraction; translation
Cellular component: cytoplasm; cytosolic large ribosomal subunit; cytosolic ribosome; extracellular exosome; membrane; cytosol; ribosome; synapse
Genetic constraint (gnomAD): Loss-of-function variants: 0 observed, 14.77 expected, observed/expected ratio (o/e) 0, 90% interval 0 to 0.2. The upper end of that interval is the gene's LOEUF score, 0.2, which puts it in group 1 of 6, group 1 being the genes least tolerant of losing a copy. Missense variants: 87 observed, 136.8 expected, observed/expected ratio (o/e) 0.64, 90% interval 0.53 to 0.76. Synonymous variants: 53 observed, 44.57 expected, observed/expected ratio (o/e) 1.19, 90% interval 0.95 to 1.5.
Homologues: Orthologues: chimpanzee RPL35A (100% identical), macaque RPL35A (100% identical), pig RPL35A (100% identical), mouse Rpl35a (99% identical), rabbit RPL35A (99% identical), dog RPL35A (95% identical), tropical clawed frog rpl35a (94% identical), zebrafish rpl35a (90% identical), Drosophila melanogaster RpL35A (61% identical), Caenorhabditis elegans rpl-33 (59% identical).
Diseases named in the same sentence as RPL35A in open-access papers:
RPL35A is named in the same sentence as 35 diseases in open-access papers, as found by Europe PMC text mining. Sharing a sentence is not in itself a finding about the gene and the disease. The quoted sentences say what the papers report.
Diamond-Blackfan anemia (14 papers, 2009 to 2024). A congenital aregenerative and often macrocytic anemia with erythroblastopenia. "The RPL35A gene is located at chromosome 3q29-qter, and almost all studies have suggested that Diamond-Blackfan anemia is caused by deletion of the RPL35A gene." (PMID 34350180, 2021). "The mutation of RPL35A contributed to Diamond-Blackfan anemia, that is an inherited bone marrow failure syndrome." (PMID 31346498, 2019). "For example, mutations in RpS19, RpS17, RpS24, RpL35a, RpS7, RpL5, RpL11, RpS10 and RpS26 have been associated with the human disease Diamond Blackfan Anemia (DBA), a dominant autosomal bone marrow failure syndrome, characterised by hypoplastic anemia with a predisposition to leukemia." (PMID 22194697, 2011). "The example of Diamond-Blackfan anemia, where mutations of different ribosomal proteins specifically affect the growth of highly proliferative erythroid progenitor cells, is a natural model of selective sensitivity of highly proliferating tumor cells to RPL35A depletion." (PMID 28223711, 2017). "Four RP genes, RPS19 RPS24, RPS17, and RPL35a are known to be mutated in Diamond-Blackfan anemia (DBA; MIM 105650), a congenital erthyroid aplasia characterized by macrocytic anemia." (PMID 19129914, 2009). "In humans, mutations in RPs have been implicated in hematopoetic disorders, most notably Diamond-Blackfan anemia (DBA), which has been attributed to mutations in RPS19, RPS26, RPS24, RPS17, RPS10, RPS7, RPL35a, RPL26, RPL11, and RPL5." (PMID 23382688, 2013). "Furthermore, IACS-010759 upregulates the expression of ribosomal protein genes such as RSP27, RPL11, RPL32, RPL35A, and RPL11, mutations which are found in osteosarcoma-prone Diamond-Blackfan anemia (DBA) patients." (PMID 34965247, 2021). "Further, mutations in several ribosomal protein (RP) genes, such as RPS19, RPL5, RPL11, RPL35A, RPS10, RPS17, and RPS24, cause Diamond-Blackfan anemia (DBA)." (PMID 38820160, 2024). "The patient tested negative for pathogenic variants in genes associated with Diamond-Blackfan anemia: RPS19, RPL5, RPL11, RPS26, RPL35a, and RPL15." (PMID 35774100, 2022). "The most well characterized is Diamond Blackfan anemia (DBA), which results from haploinsufficiencies in several different RP genes (RPS24/eS24, RPS17/eS17, RPL35A/eL33, RPL5/uL18, RPL11/uL5, RPS7/eS7, RPL36/eL36, RPS15/uS19, RPS27A/eS31) and RPS19/eS19, which is mutated in 25% of patients." (PMID 33565275, 2021).
gastric cancer (8 papers, 2021 to 2025). A primary or metastatic malignant neoplasm involving the stomach. "Of note, there is documented evidence suggesting that the ribosome protein RPL35A is linked to the advancement of both brain tumours and gastric cancer, implying that it could potentially serve as a point of focus for both diagnosis and treatment." (PMID 38436544, 2024). "Meanwhile, knockdown of RPL35A significantly suppress cell proliferation, migration, enhance apoptosis and arrest cell cycle of gastric cancer, also suggesting a role of RPL35A as a tumor promoter." (PMID 40552444, 2025). "A previous study showed that RPL35A was significantly upregulated in gastric cancer and positively correlated with tumor invasion." (PMID 38395908, 2024). "Downregulation of RPL35A significantly inhibited gastric cancer cell proliferation and migration, enhanced apoptosis and arrested cell cycle." (PMID 38395908, 2024). "Recent investigations have revealed that RPL35A potentially facilitates the advancement of gastric cancer by means of the p38/JNK signaling pathway." (PMID 38256104, 2024). "In gastric cancer, RPL35A knockdown inhibited cell proliferation and migration, promoted apoptosis, and suppressed tumor growth." (PMID 36831382, 2023). "Recent investigations have unveiled elevated RPL35A levels as an ominous predictor of poor prognosis in diverse cancers, including HCC, gastric cancer, neuroblastoma and colorectal cancer." (PMID 40552444, 2025).
hepatocellular carcinoma (4 papers, 2024 to 2025). A malignant tumor that arises from hepatocytes. "High expression of RPL35A is linked to poor prognosis in hepatocellular carcinoma." (PMID 40552444, 2025). "In addition, RPL35A was highly expressed in hepatocellular carcinoma, and was associated with poor prognosis." (PMID 38395908, 2024). "Relationship between RPL35A expression and tumor characteristics in patients with hepatocellular carcinoma." (PMID 40552444, 2025).
breast carcinoma (3 papers, 2012 to 2025). "We detected the protein level of RPL35A on numerous breast cancer cell lines using western blotting and ascertained that the expression level of RPL35A was the utmost in two TNBC cell lines, namely MDA‐MB‐231 and SUM149PT." (PMID 39871432, 2025). "Smurf2 promotes ribosomal protein L35A (RPL35A) polyubiquitination and degradation, leading to inhibition of proliferation and cell-cycle progression in breast cancer." (PMID 40978141, 2025). "On the other hand, some down-regulated ribosomal proteins, such as RPL35A, RPL18 and RPL14 that we find in both the breast cancer tissue and cell lines have received relatively little attention and might be worth pursuing." (PMID 22346740, 2012).
lung carcinoma (2 papers, 2017 to 2025). "Together, these loss-of-function experiments demonstrate that RPL35A is required for the proliferation, migration, and survival of lung cancer cells." (PMID 41241099, 2025). "Here, we demonstrate that RPL35A is upregulated in lung cancer tissues and correlates with poor patient prognosis." (PMID 41241099, 2025). "The GSEA analysis shows the significant enrichment of genes involved in aerobic glycolysis in lung cancer samples with high RPL35A expression compared to those with low RPL35A expression, suggesting a potential link between RPL35A and metabolic reprogramming." (PMID 41241099, 2025). "Collectively, these results establish RPL35A as a critical regulator of malignant behaviors in lung cancer, promoting tumor cell proliferation and migration while inhibiting apoptosis." (PMID 41241099, 2025). "Functional assays revealed that RPL35A knockdown suppresses proliferation, migration, and invasion, while promoting apoptosis in lung cancer cells." (PMID 41241099, 2025). "This study therefore aims to elucidate the functional role and mechanistic basis of RPL35A in lung cancer progression, with the goal of providing a theoretical rationale for its potential as a novel therapeutic target." (PMID 41241099, 2025). "Mechanistically, RPL35A enhances aerobic glycolysis and promotes malignant progression of lung cancer via a MYC-SKP2 signaling axis." (PMID 41241099, 2025). "Collectively, these findings indicate that RPL35A drives lung cancer progression through enhancing aerobic glycolysis." (PMID 41241099, 2025). "These gain-of-function data confirm that RPL35A is sufficient to drive oncogenic phenotypes in lung cancer cells." (PMID 41241099, 2025). "To validate this GSEA result, we assessed key indicators of aerobic glycolysis in lung cancer cells following RPL35A knockdown." (PMID 41241099, 2025). "In summary, this study reveals that RPL35A is highly expressed in lung cancer and promotes SKP2 transcription by facilitating MYC nuclear translocation and enhancing its binding to the SKP2 promoter." (PMID 41241099, 2025). "Cell counting assays demonstrated that knockdown of RPL35A suppressed the proliferation of both lung cancer cell lines." (PMID 41241099, 2025). "Functional studies show that RPL35A overexpression enhances the proliferation, migration, and invasion of lung cancer cells while suppressing apoptosis; conversely, RPL35A knockdown produces opposing effects." (PMID 41241099, 2025). "Here, we provide the first evidence that RPL35A expression is elevated in lung cancer specimens compared to adjacent normal tissues and is correlated with patient prognosis, suggesting its role as an oncogene." (PMID 41241099, 2025). "Our in vivo findings demonstrated that RPL35A promotes lung cancer tumorigenesis and suggest its potential as a therapeutic target." (PMID 41241099, 2025). "To further validate the role of RPL35A in tumorigenesis, we subcutaneously injected RPL35A-knockdown or control lung cancer cells into nude mice." (PMID 41241099, 2025). "To further investigate the molecular mechanisms by which RPL35A contributes to lung cancer progression, we performed Affymetrix microarray analysis in RPL35A knockdown and control cells." (PMID 41241099, 2025). "Our research has revealed that the expression of SKP2 is increased in lung cancer tissues, and RPL35A is positively correlated with SKP2." (PMID 41241099, 2025). "In this study, we report a novel finding: RPL35A is significantly upregulated in lung cancer tissues and contributes to tumor progression through the regulation of aerobic glycolysis." (PMID 41241099, 2025). "Analysis of gene expression profiles deposited in GEO shows that high expression level of RPL35A strongly correlated with poor survival of breast, ovarian, and lung cancer patients." (PMID 28223711, 2017). "As a ribosomal protein, RPL35A participates in diverse cellular processes, yet its role in lung cancer remains unclear." (PMID 41241099, 2025).
lung carcinoma (continued). "To test this hypothesis, we generated a rescue model in which SKP2 was overexpressed in RPL35A-knockdown lung cancer cells." (PMID 41241099, 2025). "In summary, RPL35A is upregulated in lung cancer and correlates with poor patient survival." (PMID 41241099, 2025). "Furthermore, to determine whether the oncogenic effects of RPL35A overexpression depend on glycolytic activity, we treated RPL35A-overexpressing lung cancer cells with the glycolytic inhibitor 2-DG." (PMID 41241099, 2025). "Subsequent fractionation of nuclear and cytoplasmic proteins from lung cancer cells demonstrated that upregulation of RPL35A significantly enhanced the nuclear accumulation of MYC, suggesting that RPL35A facilitate MYC’s nuclear translocation." (PMID 41241099, 2025). "Bidirectional co-immunoprecipitation (Co-IP) assays confirmed a physical interaction between RPL35A and MYC in lung cancer cells." (PMID 41241099, 2025). "Together, these findings indicate that co-targeting RPL35A and SKP2 may represent a promising strategy to suppress aerobic glycolysis and mitigate malignant phenotypes in lung cancer cells." (PMID 41241099, 2025).
neuroblastoma (2 papers, 2025). Neuroblastoma (NB) is the most common solid, extracranial childhood tumor. "In neuroblastoma, the knockdown of RPL35A has been demonstrated to exert negative regulatory control over the ERK pathway, inhibit HIF1α expression and impede aerobic glycolysis." (PMID 40552444, 2025).
ovarian carcinoma (2 papers, 2024 to 2025). A malignant neoplasm originating from the surface ovarian epithelium. "High expression of RPL35A in patients with ovarian cancer was clinically associated with short survival and poor TNM staging, suggesting its potential as a diagnostic and prognostic marker for this disease." (PMID 38436544, 2024). "Additionally, analysis of clinically collected medical records of ovarian cancer patients showed that high expression of RPL35A was associated with shorter overall survival and disease‐free survival (p < 0.001)." (PMID 38436544, 2024). "Mechanically, RPL35A promoted the direct binding of transcription factor YY1 to CTCF in ovarian cancer cells." (PMID 38436544, 2024). "Ovarian cancer cells with interfered expression of RPL35A and CTCF were inoculated into nude mice by subcutaneous injection to establish xenograft tumour model." (PMID 38436544, 2024). "Consistently, the expression of RPL35A in ovarian cancer cell lines (HO‐8910, SK‐OV‐3, OVCAR‐3) was significantly higher than that in normal ovarian epithelial cells IOSE80, especially in HO‐8910 and SK‐OV‐3 cell lines (p < 0.001)." (PMID 38436544, 2024). "Loss/gain‐of‐function experiments were conducted to reveal the role of RPL35A in the phenotypes of ovarian cancer." (PMID 38436544, 2024). "Functionally, RPL35A knock down inhibited ovarian cancer cell proliferation and migration, enhanced apoptosis, while overexpression had the opposite effect." (PMID 38436544, 2024). "Functionally, RPL35A affected the proliferation and apoptosis of ovarian cancer cells through PPAR signalling pathway." (PMID 38436544, 2024). "In order to determine the clinical relevance of RPL35A in human ovarian cancer, the expression patterns of RPL35A were examined in ovarian cancer tissues (n = 107) and corresponding normal tissues (n = 8) using IHC staining." (PMID 38436544, 2024). "Ovarian cancer cells with RPL35A knockdown and overexpression were evaluated for changes in their migration capacity by wound‐healing experiment and B Transwell tests." (PMID 38436544, 2024). "This high expression of RPL35A is clinically associated with short survival and poor TNM staging in ovarian cancer patients." (PMID 38436544, 2024). "The wound‐healing assay demonstrated a suppressed cell migration ability in ovarian cancer cells when RPL35A was knocked down (p < 0.001)." (PMID 38436544, 2024). "More specifically, RPL35A promotes the direct binding of the transcription factor YY1 to CTCF in ovarian cancer cells." (PMID 38436544, 2024). "Functionally, RPL35A knock down inhibits ovarian cancer cell proliferation and migration, enhances apoptosis, while overexpression has the opposite effect." (PMID 38436544, 2024). "In order to reveal the molecular mechanism of RPL35A regulating the progression of ovarian cancer, the following researches were carried out." (PMID 38436544, 2024). "In this study, the role of human ribosomal protein l35a (RPL35A) in ovarian cancer was explored in vitro and in vivo." (PMID 38436544, 2024). "Functional tests were performed both in vitro and in vivo in this study to confirm the impact of RPL35A on the advancement of ovarian cancer cells through facilitating the direct interaction between YY1 and CTCF." (PMID 38436544, 2024). "The data obtained from the cell counting assay indicated a decrease in the proliferative activity of ovarian cancer cells with RPL35A knockdown (p < 0.001)." (PMID 38436544, 2024). "Firstly, we identified RPL35A expression in ovarian cancer based on databases and clinical tissue samples." (PMID 38436544, 2024). "In order to further understand the roles of RPL35A and CTCF in ovarian cancer cells, a sequence of assays involving loss/gain of their function were conducted both in vitro and in vivo." (PMID 38436544, 2024). "This study has explored and revealed the role of RPL35A in ovarian cancer, considering the information provided above." (PMID 38436544, 2024).